SIM2 (SIM bHLH transcription factor 2)
Diseases named in the same sentence as SIM2 in open-access papers (continued):
Sharing a sentence is not in itself a finding about the gene and the disease.
tumor (21 papers, 2010 to 2025). "SIM2 is associated with tumor invasiveness and reduced cancer-specific survival and could serve as a potential marker for early detection of PCa." (PMID 38201640, 2024). "Induction of STING activity was found to be dependent on the breast tumor suppressor gene single-minded 2 (SIM2)." (PMID 39399905, 2024). "SIM2 was upregulated in the paired tumor tissues compared with paired normal tissues (P < 0.001), and was downregulated in the CD24low group compared with CD24high group (P = 0.0014)." (PMID 36882451, 2023). "In this study, we discovered a novel mechanism by which SIM2 suppresses tumor growth by directly interacting with MRCs to promote proper complex formation and SC assembly, leading to increased OXPHOS rates." (PMID 37121978, 2023). "Coincidently, SIM2s overexpression also significantly decreased COX-2 staining in tumor sections and all point toward a role for SIM2 in preventing metastasis." (PMID 31783895, 2019). "In line with previous studies in prostate cell lines and tissues, the present study recorded an increase in the expression of SIM2 in tumor tissues compared to the SNT (FC = 7.85, P < 0.001, FDR < 0.001)." (PMID 28910345, 2017). "SIM2-knockdown SKG-ΙΙΙa cell lines (SIM2 shRNA #13 and #15) were subcutaneously grafted to immunodeficient mice and monitored for tumor progression." (PMID 29109451, 2017). "In our study, we found the promoter methylation level of SIM2 in primary tumor was upregulated." (PMID 36882451, 2023). "Moreover, we show that the proliferation of VCaP cells and their tumor size are affected by SIM2 expression." (PMID 34127815, 2021). "Furthermore, SIM2 knockdown suppressed tumor growth with increased HIF-1α expression and angiogenesis in vivo." (PMID 29109451, 2017). "SIM2-s was also found to have tumor suppressive activity in breast cancer." (PMID 22174909, 2011). "In contrast, the upregulated gene set (e.g., SIM2, MYBL2, HJURP) was overexpressed in up to 22 cancers, indicating an oncogenic-like role and participation in common tumor-promoting pathways." (PMID 41439026, 2025). "In support of this, we found that the SIM2 peptide, corresponding to the C-terminal SIM of DAXX, inhibits de novo lipogenesis and suppresses in vivo tumor growth." (PMID 37045819, 2023). "Concordantly, SIM2 was effective to inhibit de novo lipogenesis in ER + BC and TNBC cell lines and effectively inhibited in vivo tumor growth of basal/TNBC tumor models." (PMID 37045819, 2023). "Among the most overexpressed genes in tumor cells compared to normal tissue were the transcription factors HOXB9, SIM2, ZIC5, SP8, TFAP2A, FOXE1, HOXB13, and SALL4; the cancer testis antigen CT83; and the cytokine IL23A." (PMID 37228492, 2023). "In line with the results from the cell culture experiments, SIM2 silencing similarly to AR depletion decreased tumor size of VCaP cells in CAM assays, which further points to the importance of SIM2 in the regulation of CRPC cells." (PMID 34127815, 2021). "The most frequently differentially hypomethylated CpG islands different between the normal and tumor tissues were TACSTD2, followed by SIM2 and DAPK1." (PMID 31675985, 2019). "Previously, we have shown that Singleminded-2s (SIM2s; expressed from SIM2), a member of the bHLH/PAS family of transcription factors, is a tumor suppressor that is expressed in breast epithelial cells and downregulated in the transition from DCIS to IDC." (PMID 31783895, 2019). "Five genes (62.5%) demonstrated tumour acquired methylation (EMILIN2, SALL1, DBC1, FBLN2 and CIDE-A), whilst the remaining 3 (COMP, EPSTI1, SIM2) showed equal methylation in the corresponding normal breast tissue DNA." (PMID 20205715, 2010). "Among the most overexpressed genes in tumor cells compared to normal tissue are genes coding for transcription factors (HOXB9, SIM2, ZIC5, SP8, TFAP2A, FOXE1, HOXB13, and SALL4), cancer testis antigens (CT83), and cytokines activating regulatory Th17 cells (IL23A)." (PMID 37228492, 2023).
tumor (continued). "SIM2 bound to SUMO1 in vitro and blocked de novo lipogenesis in various types of cancer cells, including breast (MDA-MB-231, MDA-MB-468 and Hs578T), prostate (R1-AD1 and R1-D567), colon (HCT116), and mouse tumor cells (4T1 and CT26.CL25)." (PMID 37045819, 2023). "Conversely, the upregulated gene subset (e.g., SIM2, HJURP, IQGAP3, KIF18B) showed predominantly negative correlations with many IRGs, potentially reflecting an association with the suppression of anti-tumor immune responses." (PMID 41439026, 2025).
cancer (17 papers, 2011 to 2025). A tumor composed of atypical neoplastic, often pleomorphic cells that invade other tissues. "Since SIM2 has a Jekyll-and-Hyde character and role allotment of its splicing variants is still unclear, it is important to integrate their bona fide roles by cancer type." (PMID 29109451, 2017). "About this notion, we first investigated the SIM2 mRNA level in CvSCCs among various types of cancer by RNA sequencing dataset that consisted of 8449 cancer patients from The Cancer Genome Atlas (TCGA) database." (PMID 29109451, 2017). "Aberrant expression of SIM2 has been reported in several types of cancers including prostate, colon, and pancreatic cancer." (PMID 29109451, 2017). "To further investigate the suitability of this gene as a target for immunotherapy, we used the Oncomine database to examine the expression of SIM2 in other cancers." (PMID 24690990, 2014). "Together, these studies suggest that SIM2 is an attractive immunotherapeutic target for a range of different cancers." (PMID 24690990, 2014). "Together, these data indicate that SIM2 is an attractive immunotherapeutic target for a wide range of cancers." (PMID 24690990, 2014). "Despite its suspected role in cancer, very little is known about the contribution of the transcription factor SIM2 to the regulation of gene expression." (PMID 22174909, 2011). "Among them, three genes (DMC1, PENK, and SIM2) were selected for further independent validation with additional normal tissues and BCa tissues because the genes showed higher methylation levels in all cancer tissues than in normal tissues." (PMID 36403035, 2022). "Current knowledge about misregulation of SIM2 in cancer is obtained from studies regarding SIM2s." (PMID 29109451, 2017). "Interestingly, the list of SIM2 targets was also enriched for genes involved in cancer pathways, as revealed by the KEGG pathway analysis (p = 1.46e-04)." (PMID 25955728, 2015). "Furthermore, 3 out of 10 were epigenetically regulated by PRC2 in ES cells (TWIST1, ISL2 and SIM2), suggesting an important role of methylation events on these genes affecting cell differentiation processes and cancer." (PMID 23468990, 2013). "Additionally, we found that many other cancers overexpressed SIM2." (PMID 24690990, 2014). "Despite this, our data showed that individuals with PSA level ≤ 4.0 ng/mL can be distinguished into cancer-free or PCa-affected based on the expression levels of OR51E2 and SIM2 genes." (PMID 28910345, 2017). "We used SUM159 cells as a model system, as they do not express basal levels of SIM2, allowing us to overexpress SIM2 to investigate its functional roles in cancer." (PMID 39399905, 2024). "We were not able to validate TMPRSS2 fusions with CASZ1, SIM2, and C1orf61 due to the insufficient amount of RNA; however, all these genes are known to play roles in pathologic conditions, including cancers." (PMID 37300660, 2023). "As such, pLPCX-SIM2s-FLAG was then transduced into SUM159 TNBC cancer cell line, which endogenously expresses low levels of SIM2 (data not shown)." (PMID 31775907, 2019). "Our results do not imply that ETS2 and SIM2 are the only TFs in the HSA21 with a role in oncogenesis because several other TFs, located in the HSA21, also have association with malignancies." (PMID 23343470, 2013).
SIM2 also shares sentences with these, for which no sentence is quoted: breast tumor (2 papers); esophageal SCC (2); adenocarcinoma (1); adenoma (1); Alzheimer disease (1); bladder tumors (1); bone metastasis (1); breast invasive carcinoma (1); cardiac hypertrophy (1); cardiomyopathies (1); cardiovascular diseases (1); cervical cancer (1); cervical squamous cell carcinoma (1); Cognitive impairment (1); developmental delay (1); Huntington disease (1); immune deficiency (1); liver cancer (1); lung carcinoma (1); lupus (1); lymph node- metastasis (1); oligodendroglioma (1); Parkinson disease (1); prostate (1); seizure disorders (1); skin cancer (1); type 2 diabetes (1).